CD46 (CD46 molecule)
Diseases named in the same sentence as CD46 in open-access papers (continued):
Sharing a sentence is not in itself a finding about the gene and the disease.
infection (continued). "Next, we infected HeLa cells with A. nosocomialis M2 expressing CpaA and CpaAE520A at three different multiplicities of infection (MOI) (10, 100, and 1,000) and used flow cytometry analysis to quantify the levels of cell surface exposed CD55 and CD46 postinfection." (PMID 33024038, 2020). "However, when the CD46-MDBK cells were incubated for 72 h, a complete infection of the cell layer was visible for all isolates (passage 15), that differed markedly from incubation for 72 h with the passage 0 virus." (PMID 32781607, 2020). "As CD46 is also a receptor for various other pathogens such as the human herpes virus HHV-6, the BVDV pestivirus and adenoviruses B and D, the CD46-Cyt-1-GOPC-VPS34-BECN1 complex axis is likely to also trigger autophagy during infection by those microbes." (PMID 32274388, 2020). "Fibroblast cell lines (MRC5 and HFF-1) express CD46 but do not show inhibition of infection when CD46 is targeted with mAbs or knocked down with siRNA." (PMID 31221976, 2019). "The function of CD46 during infection extends beyond its expression on the cell surface and importantly, CD46 expression alone does not confer dependency of virus entry." (PMID 31221976, 2019). "In addition, MeV induces autophagy through the CD46-Cyt-1/GOPC pathway, which indicates that a cell surface pathogen receptor can directly trigger autophagy, a critical step for controlling infection." (PMID 30067475, 2018). "Group B adenoviruses (such as Ad11p) show no infection at all, likely because the main receptor for group B adenoviruses (CD46) is not expressed in most murine or hamster cells." (PMID 29898782, 2018). "Exposure to nectin-4 blocking antibody was permissive for MV-GFP infection (high mean fluorescence) while the exposure to CD46 blocking antibody (low mean fluorescence) was not." (PMID 28968974, 2017). "MV-infected CD46+/IFNγ-KO explants displayed significantly lower nestin expression compared to MV-infected CD46+ mice, which displayed no change with infection." (PMID 27178303, 2016). "As one would anticipate, polyclonal antibodies directed against CD46 did not inhibit infections of activated B cells with the wild-type virus." (PMID 27657109, 2016). "Under these conditions, both inhibitors blocked more than 80% of Ad43 transduction of each cell line, suggesting that, irrespective of CD46 expression, the virus can use integrins for attachment and infection." (PMID 27462785, 2016). "Most of the CD46+ pups succumb to the infection between 9–12 dpi regardless of IFNγ expression, and it is unclear why the CD46+ pups would demonstrate a decline in inflammatory signaling pathways when the virus is still present." (PMID 27178303, 2016). "Again, these adenocarcinoma cell lines did not express SLAMF1 nor were wtMeV infections blocked by antibodies against MCP/CD46 or SLAMF1." (PMID 27657109, 2016). "Ad35 vectors recognize human CD46, not CAR, as the cellular receptor for infection; because human CD46 is expressed in almost all human cells, Ad35 vectors demonstrate broad tropism to human cells." (PMID 25015402, 2014). "We confirmed these results and further demonstrated that infections with a recombinant wtMV engineered to express EGFP (IC323-EGFP wtMV) were independent of CD46 (MCP) and CD150 (SLAM) expression." (PMID 21901103, 2011). "CD46 was blocked with polyclonal antibodies against CD46 before infection but no inhibition of bacterial adherence was detected (data not shown)." (PMID 21949708, 2011). "We also analyzed MVEdm replication in the presence of increased levels of its own receptor CD46, but we did not observe any negative influence of CD46 overexpression on productive MVEdm infection (data not shown)." (PMID 19108727, 2008). "After 3 days of infection, T4 levels increased in nontransgenic mice as the mice recovered, whereas T4 levels were undetectable in CD46 transgenic mice after 2 days, which then had a lethal outcome." (PMID 17311106, 2007).
infection (continued). "Nonetheless, infections with either the serum samples or input viruses on MDBK, CD46Δ, and CD46 A82LPTFS cells showed that the PI-86-2022 virus was capable of infecting both of the CD46-edited cell lines more efficiently compared to the original PI-86-2021 isolate." (PMID 40431646, 2025). "Similarly, a CD46-edited heifer calf expressing the CD46 A82LPTFS receptor variant had dramatically reduced susceptibility to BVDV as measured by reduced clinical signs and a lack of infection in white blood cells following challenge." (PMID 40431646, 2025). "Interestingly, DSG2-negative cell line MIA PaCa-2 even showed resistance to JO4 vector infection, possibly due to the negative effect of JO4 mutation on the usage of another Ad3 receptor: CD46." (PMID 36016457, 2022). "The absence of the CD46 or HS could not completely block the infection of host cells infected by BVDV, indicating that the key receptor molecules that specifically mediate the invasion of BVDV into target cells are still unknown." (PMID 36298858, 2022). "Furthermore, the infection of epithelial cells with BVDV did not affect the polarized location of CD46." (PMID 33300445, 2021). "Being an apical protein, bovine CD46 can mediate apical infection but not basolateral infection." (PMID 33300445, 2021). "Thus, the results revealed that human A498 cells, but not animal cells, express CD46 cell surface receptors that enable RCAd11p infection." (PMID 34777270, 2021). "The importance of CD46-cyt1 downregulation to Ngo infection is not understood." (PMID 30753248, 2019). "However, it remains to be determined whether Ngo can accelerate CD46-cyt1 and LAMP1 degradation at high MOI condition used in HeLa cell infection." (PMID 30753248, 2019). "Therefore it can be concluded that in contrast to CAR, CD46 plays a role for HAdV17GFP infection, whereas DSG2 has no role as receptor for HAdV17GFP infection." (PMID 30194327, 2018). "In summary we concluded that HAdV17GFP infection preferentially depends on CD46 rather than CAR." (PMID 30194327, 2018). "The ability of shp65/RelA-expressing HeLa cells to sustain an efficient MeV replication was not due to a better infection of these cells since we observed an equivalent level of expression of the MeV cell surface receptor CD46 on shp65/RelA- and shControl-expressing cells." (PMID 28531150, 2017). "Moreover, STAT1β-P/STAT1β ratios declined during infection in CD46+/IFNγ-KO explants, but not CD46+ explants." (PMID 27178303, 2016). "Infection of Vero cells was not inhibited by anti-CD46 antibody." (PMID 25171206, 2014). "In summary, the data support a dual role of HSPGs in Ad35 infection: They act as alternative low-affinity receptors for CD46-independent infection (in the absence of CD46 expression) but they also represent a physical barrier between Ad35 and CD46 (in the presence of CD46 expression)." (PMID 18974862, 2008). "In response to infection, T4 levels dropped in both CD46 transgenic mice and nontransgenic mice." (PMID 17311106, 2007). "However, infection was not completely abolished in A594-ΔCD46 cells, suggesting that additional cell surface molecules may either facilitate infection or compensate for the absence of CD46." (PMID 40980888, 2025). "Furthermore, competition assays with pseudotyped viruses suggested that the interaction of the HAdV-11 fiber with DSG2 was not required for infection but that DSG2 could serve as a receptor in the absence of CD46." (PMID 37921471, 2023). "Thus, HAdV55 may recognize tree shrew desmoglein-2 but not CD46 for infection; however, a series of experiments needs to be performed to draw a conclusion." (PMID 33622191, 2021). "An important aspect of MV infection is the down regulation of CD46 and SLAM from the cell surface following MV-H expression To determine whether PVRL4 expression was down regulated in a similar manner, FACS analysis of PVRL4 surface expression was performed at 48 h post infection." (PMID 21901103, 2011).
infection (continued). "Even when some experiments suggest that porcine CD46 plays an important role in CSFV infection, the absence of complete inhibition of the infection after using antibodies directed against the protein, suggests the involvement of other entry factors." (PMID 38041163, 2023). "Infection with mLOAd703 induced expression of both CD40L (∼50%positive) and 4-1BBL (∼70% positive), but did not significantly alter CD46 levels." (PMID 35141399, 2022). "Porcine cell lines that do not express CD46 were shown to be non-permissive to APPV infection, while porcine pestiviruses such as CSFV and BuPV efficiently infected these cells, indicating a CD46-independent mechanism of entry." (PMID 34204224, 2021). "No significant inhibition of infection was observed in AD169BADrUL131 infected MRC5 and HFF-1 CD46-KD cells." (PMID 31221976, 2019). "Evidence for in vivo usage of CD46, i.e., infection of CD150-/nectin-4- cells, was not obtained during these studies even though there are enormous numbers of CD46-positive cells in close proximity to MV-infected centers." (PMID 29263877, 2017). "Together, these results demonstrate that activation of STAT signaling molecules does not differ significantly early in infection (3 dpi), but that STAT1 and STAT2 phosphorylation occurs later infection in CD46+ and CD46+/IFNγ-KO explants." (PMID 27178303, 2016). "GFAP levels were elevated significantly with infection in CD46+ mice, but not in CD46+/IFNγ-KO mice, in comparison to uninfected controls at 7 dpi, suggesting that localized reactive astrogliosis may be occurring in the hippocampus in the presence of IFNγ during infection." (PMID 27178303, 2016). "This vector belongs to subgroup B and recognizes human CD46, rather than CAR, as a cellular receptor for infection." (PMID 25015402, 2014). "Conversely, a decrease of up to 50% in CD46 intensity, but no obvious effect on CAR intensity, was observed in cultures following infection with Ad5F35-CRAD." (PMID 20041185, 2009). "However, in this case CD46 was shown to be the major attachment factor, while both CAR and SA did not mediate infection." (PMID 39883726, 2025). "We then investigated whether a virulent strain of MeV, which does not bind CD46 but CD150 to infect cells, might also induce the two waves of autophagy during infection, and exploit autophagy in HeLa cells." (PMID 24086130, 2013).
cancer (97 papers, 1993 to 2026). A tumor composed of atypical neoplastic, often pleomorphic cells that invade other tissues. "These and other similar studies point to the potential value of utilizing CD46 as a diagnostic and prognostic indicator for certain cancer types." (PMID 40309774, 2025). "CD46-ADCs are novel compounds consisting of cytotoxic agents linked to the CD46 antibody that are able to specifically recognize CD46 expressed on the surface of cancer cells." (PMID 38919630, 2024). "In other words, CD46 is highly expressed in low risk cancer patients and is poorly expressed in high risk cancer patients." (PMID 30201920, 2018). "It has also been demonstrated that CD46 is implicated in the development and progression of several cancers." (PMID 27203670, 2016). "CD46 has been implicated in the development and progression of several cancer types." (PMID 27203670, 2016). "The high affinity Ad35K++ cross-links several CD46 molecules on cancer cells, resulting in the shedding of CD46’s ectodomain and internalization of the remainder." (PMID 40309774, 2025). "Studying the roles of CD46 in cancer biology is hampered, because mice, an often-used oncologic model system, as well as other subprimates have very restricted expression of CD46." (PMID 40309774, 2025). "Oncolytic AdVs that specifically target CD46 represent an innovative approach in cancer treatment that leverages CD46 binding with the lytic and other capabilities of AdVs." (PMID 40309774, 2025). "What is consistent, though, is that when cancers lead to aberrantly high expression of CD46, the traditional role of complement as an antitumor effector, especially in association with therapeutic cancer-targeting mAbs, can be disrupted." (PMID 40309774, 2025). "(d) Perhaps the most promising avenue in the fight against cancer will be in utilizing CD46-targeted approaches in combination with other therapeutics, such as immune checkpoint inhibitors, chemotherapy, or radiotherapy." (PMID 40309774, 2025). "Several investigations have sought possible mechanisms examining the effects of CD46 in facilitating cancer invasion and/or metastatic potential." (PMID 40309774, 2025). "From these and other reports, it is clear that CD46 plays multiple roles in the progression of cancer." (PMID 40309774, 2025). "A preclinical study using cancer cell lines as well as a murine xenograft model system compared a species C CAR-targeting Ad5 vector to a species B CD46-targeting Ad35 to create an Ad5/35 chimera." (PMID 40309774, 2025). "The findings of this and similar investigations encourage the further dissection of signaling pathways impacted by CD46 expression and their disruption as an avenue for cancer therapeutics." (PMID 40309774, 2025). "It is worth noting that despite the increasing number of cancer therapeutic approaches using these chimeric vectors, CD46 expression in various cancer types needs to be assessed in individual patients to predict the immune response and patient outcomes." (PMID 38919630, 2024). "Oncolytic MeV- and Ad5-based vectors (targeting CD46) have been exploited as popular vectors for cancer therapeutic applications, including vaccines." (PMID 38919630, 2024). "CD46 is a membrane protein involved in regulation of the complement and is frequently upregulated in cancer cells to primarily evade antibody‐mediated cytotoxicity." (PMID 38037840, 2024). "CD46 is one of the primary receptors utilized by BMECs to take up exosomes derived from brain metastatic cancer cell lines and promote cancer metastasis." (PMID 38890722, 2024).
cancer (continued). "It has been demonstrated that targeted downregulation of CD46 expression by siRNA in vitro increases the sensitivity of cancer cells to CDC." (PMID 38919630, 2024). "Overall, these findings suggest that both adenoviruses can infect CD46-expression cancer cells and synthesize copGFP." (PMID 39886667, 2024). "Compared to normal cells, cancer cells have high expression of receptors on their surface, such as CD46, which facilitates the targeting of oncolytic viruses such as measles virus and adenovirus to cancer cells." (PMID 39697335, 2024). "To assess the performance of sABEv3.22 for inducible gene knockout, we targeted two genes expressing Beta-2 microglobulin (B2M) or CD46 regulatory proteins that have been widely studied in the context of allogeneic cell therapies and cancer research." (PMID 37696818, 2023). "The expression of CD46 was significantly more homogeneous than that of the patient's primary cancer cells." (PMID 37621847, 2023). "In this study, the role of CD46 in protecting the cancer cells from CDC and cetuximab-mediated cell cytotoxicity was investigated." (PMID 36575233, 2022). "In contrast, patients in the high-risk group were enriched in expression genes of cancer-promoting inflammation such as ITGB1 and CD46." (PMID 35832540, 2022). "Most adenoviruses use the Coxsackie Adenovirus receptor (CAR) to infect cells, but some species (HAdV-B) enter the cell through binding to the complement regulatory protein CD46, which is ubiquitously expressed on many cancer cells." (PMID 36140243, 2022). "The frequent overexpression of CD46 in malignant tumors has provided a basis to use vaccine-lineage measles virus (MeV) as an oncolytic virotherapy platform." (PMID 33534834, 2021). "The overexpression of CD46 in many different human cancers makes it a reasonable target of OVs and antibody-drug conjugated therapies." (PMID 33534834, 2021). "The roles of TIPRL/LC3/CD133/CD44/CD46 in liver normal and cancer cell lines were determined by in vitro studies." (PMID 34208132, 2021). "Vaccine strains of the measles virus (MeV) have been shown to be promising anti-cancer agents because of the frequent overexpression of the host-cell receptor CD46 in human malignancies." (PMID 33534834, 2021). "For example some oncolytic viruses use cell surface molecules for entry that are abnormally upregulated in cancer cells, such as CD46 for MV, which is frequently overexpressed to avoid immune system recognition and elimination." (PMID 33668361, 2021). "In cancers originating from epithelium, however, CD46 is located in cellular junctions which are hard to reach for adenoviral vectors." (PMID 32957644, 2020). "STAT3 is often constitutively active in cancer cells, explaining why CD46 expression is often upregulated." (PMID 32957644, 2020). "Future studies addressing CD46-driven metabolic reprogramming are warranted to address its oncologic implications in cancer." (PMID 33147799, 2020). "Alternatively, some species B adenoviruses target CD46, thus presenting an improved approach to increase the effectiveness of cancer targeting." (PMID 33147799, 2020). "The success of pre-clinical studies utilizing CD46 as a therapeutic target have now led more than 20 clinical trials being conducted for cancer treatments." (PMID 33147799, 2020). "CD46 is emerging as an important player in both malignant transformation as well as in cancer immunotherapy." (PMID 33147799, 2020). "CD46 expression protects a cell from complement-dependent cytotoxicity, so expression in a cancer cell promotes escape from immune surveillance and provides the cancer cell with a strong survival advantage." (PMID 33291506, 2020). "As a result, there are multiple early-phase clinical trials targeting CD46 to treat a variety of cancers." (PMID 33147799, 2020). "LOAd viruses infect cells via the complement regulator CD46, which is frequently overexpressed in many cancer types including MM." (PMID 32355275, 2020).